INS (insulin)
Diseases named in the same sentence as INS in open-access papers (continued):
Sharing a sentence is not in itself a finding about the gene and the disease.
magnesium deficiency (continued). "Iron deficiency has been related to improved insulin sensitivity in animal models." (PMID 22292925, 2012). "Interestingly, despite a more modest induction of iron deficiency for the current study (hemoglobin = 80 g/L), relative elevations in serum glucose and insulin levels were still observed in both the 76-ID and 93-ID groups." (PMID 23110872, 2012). "Iron deficiency could have effects on the liver, pancreatic beta cells, adipose tissue and brain that might affect insulin production, whole body insulin action and glucose uptake and metabolism." (PMID 21589859, 2011). "Moreover, magnesium deficiency may also contribute to systemic inflammation and oxidative stress, which further impair insulin sensitivity." (PMID 40895688, 2025). "Magnesium deficiency is hypothesized to affect glycemic control by altering cellular glucose transport, reducing pancreatic insulin secretion, and defective post-receptor insulin signaling." (PMID 40169565, 2025). "Additionally, magnesium deficiency may interfere with enzymatic reactions in the insulin signaling pathway or induce inflammation or oxidative stress, thereby affecting glucose metabolism." (PMID 39149550, 2024). "In addition to potentially inaccurate HbA1c, iron deficiency may directly worsen glycemic control through effects on insulin synthesis, glucose metabolism, and oxygen delivery." (PMID 38149144, 2023). "Conversely, insulin enhances hepcidin synthesis in liver cells by activating STAT3 via the JAK/STAT signaling pathway, potentially leading to iron deficiency." (PMID 41515226, 2025). "Among INS-GAS mice, MIP-1α and IL-17 were significantly increased in infected mice under conditions of iron deficiency compared with infected mice on an iron-replete diet." (PMID 35316215, 2022). "Interestingly, even a moderate induction of iron deficiency appears to contribute to elevations in both steady-state levels of serum glucose and insulin regardless of basal diet formulation." (PMID 23110872, 2012).
-dependent (53 papers, 2001 to 2025). "T1DM (insulin-dependent) is an autoimmune condition that causes the body to attack and destroy the insulin-producing cells, causing dysfunction of the pancreas in secreting insulin." (PMID 41154479, 2025). "Type I DM (also known as insulin-dependent or IDDM) is primarily caused by the destruction of insulin-secreting beta-cells in the pancreatic islets leading to deficient insulin production in the body." (PMID 32708678, 2020). "In insulin-dependent diabetic patients, the low insulin levels can lead to osteopenia, increased risk of fragility fracture, and poor bone healing." (PMID 29138637, 2017). "The study is designed to build on a delimited set of intervention components of presumed greatest importance to people with non-insulin-dependent T2D to help prioritize the components in the planned randomized controlled trial." (PMID 38778345, 2024). "Previous research indicated that HNF1A-KO mice exhibit a phenotype resembling Laron-type dwarfism and non–insulin-dependent DM, likely due to a decrease in the expression of insulin-like growth factor I and lower insulin levels." (PMID 37219942, 2023). "The 24-hour urinary CPR <20 μg/day, fasting CPR <0.48 ng/m, and ΔCPR <1.0 ng/mL in glucagon test have been used as indices of insulin dependence." (PMID 35574023, 2022). "In conclusion, our results indicate that both intestinal dysbiosis and altered fecal BA levels are present in dogs with naturally occurring, insulin-dependent DM." (PMID 31316997, 2019). "Thirteen percent of already insulin-dependent diabetics at the time of admission left the hospital with an increased dose of insulin." (PMID 30691499, 2019). "On the other hand, type 2 DM (non-insulin-dependent) is characterized by insulin resistance, a condition when this hormone does not act correctly, even if its serum concentration is high." (PMID 30088548, 2018). "Keywords such as “insulin secretion” and “immunosuppression” increased in frequency between the 1970s and the 2000/10s, whereas keywords such as insulin dependence, rejection, survival, and encapsulation peaked during the 1990s." (PMID 29095254, 2017). "In the insulin-dependent diabetic rats, the combination of vanadium and insulin therapy (a minimum injection dose of insulin) and also one-year time are needed to extend normoglycemia after the withdrawal of insulin or vanadium." (PMID 26459400, 2016). "Therefore another important area of study would be to investigate the effects of herbal-derived active metabolites in insulin and insulin-like growth factor-dependent cancers." (PMID 38531974, 2024). "DWP16001 was applied to dogs with insulin‐dependent DM in this study." (PMID 38686463, 2024). "In the present study, 44.5% of DM patients were insulin-dependent." (PMID 37526706, 2023). "DM is mainly classified as type I (insulin-dependent) due to immune-mediated beta cells destruction, leading to insulin deficiency; and type II (non-insulin-dependent) due to insulin-secreting defect and insulin resistance." (PMID 35453355, 2022). "On this basis, PTS could be used as pure active principle or in its functional food preparations to assist the therapy of insulin-dependent metabolic disorders." (PMID 32585851, 2020). "In vitro and in cell assays gave evidence of the pterostilbene ability to reduce insulin secretion on glucose-stimulated pancreatic beta cells, opening the way to potential applications of pterostilbene as a supplement in the care of insulin-dependent metabolic disorders." (PMID 32585851, 2020). "Therefore, the aim of this feasibility study is to evaluate the feasibility of two telemonitoring designs for people with non-insulin-dependent T2D with a goal of identifying the optimal telemonitoring intervention for a planned future large-scale randomized controlled trial." (PMID 38778345, 2024).
-dependent (continued). "It was later recognized that the binding of SARS-CoV2 to its receptor, angiotensin converting enzyme 2 (ACE2), in the endocrine section of the pancreas, may directly damage pancreatic islets and reduce insulin secretion, leading to transient insulin-dependent DM." (PMID 32708504, 2020). "Additionally, the addition of 16 g of guar and 10 g of pectin to a meal containing 106 g of carbohydrates significantly reduced postprandial glucose and insulin levels in both insulin-dependent and non-insulin-dependent diabetics." (PMID 39458444, 2024). "However, it is essential to note that insulin therapy is not suitable for all patients, such as those with non-insulin-dependent DM, for whom insulin therapy is a last resort." (PMID 37090383, 2023). "Similar result was also found between insulin-dependent DM and non-insulin-dependent DM." (PMID 34485399, 2021).
Adrenal insufficiency (52 papers, 2008 to 2025). Insufficient production of steroid hormones (primarily cortisol) by the adrenal glands. "Virus-infected, prothrombin-depleted mice also displayed similar plasma cortisol and insulin levels as control-infected animals, decreasing the likelihood of adrenal insufficiency or acute metabolic abnormalities as the cause of death." (PMID 39820014, 2025). "In addition, unrelieved pain induces prolonged stress on biologic systems and may predispose patients to adrenal insufficiency, alterations of immune function as well as glucose metabolism by increasing resistance to insulin." (PMID 23883683, 2013). "Logistic regression analyses of HbA1c, C-peptide, and basal insulin doses revealed distinct differences, suggesting a potential link between adrenal insufficiency (AI) and autonomic neuropathy." (PMID 40932945, 2025). "It was suggested that euglycemic diabetic ketosis was induced by the self-suspension of insulin and insulin secretagogues, adrenal insufficiency, SGLT2 inhibitors, and carbohydrate intake shortage." (PMID 38414717, 2024). "Two patients with additional irAEs received high dose prednisone on discharge and required 0.29 to 0.85 units/kg/day of insulin while the patient with adrenal insufficiency on chronic hydrocortisone required 0.4 units/kg/day of insulin." (PMID 32733645, 2020). "The short synacthen test (SST) has replaced the insulin tolerance test as first line in the investigation of adrenal insufficiency." (PMID 24616759, 2013). "Recovery of adrenal insufficiency in our series was assessed within 18 months after surgery, similar to Berg’s study, in which hypocortisolism was evaluated by insulin-tolerance test 12 months after surgery." (PMID 22661135, 2012). "Certain differential diagnoses to be considered include oral hypoglycemic agents, insulin, consumption of alcohol, critical illness like renal, cardiac, hepatic failure, or sepsis, pituitary insufficiency or adrenal insufficiency, or endogenous surplus of insulin or insulin-like growth factors." (PMID 39188435, 2024). "The insulin test is considered the gold standard for diagnosing adrenal insufficiency." (PMID 36465638, 2022). "The fallen blood glucose maybe results from improper insulin or oral drug use, long fasting or digestive impairment, impaired counter-regulation partial adrenal insufficiency, all of which pushed people into poor prognoses." (PMID 36572923, 2022). "These patients might not present with the classical clinical features of hyperprolactinemia, and instead, they present with frequent hypoglycaemia and decreased insulin requirement due to secondary adrenal insufficiency as a consequence of the mass effect of the prolactinoma." (PMID 35070533, 2021). "Three kinds of stimulation tests were applied to prove secondary adrenal insufficiency (AI) in the literature, namely, corticotrophin-releasing hormone (CRH) stimulation test, ACTH stimulation test, and insulin hypoglycemia test (IHT)." (PMID 38318292, 2024). "For women with adrenal insufficiency, 50 mg DHEA treatment for 3 months significantly improved insulin sensitivity." (PMID 35784547, 2022). "The patient did not use insulin, serum sulfonylurea screen was negative, and testing for adrenal insufficiency was unremarkable." (PMID 38405103, 2024). "On the other hand, DHEA supplements have not shown definitive effects in cardiovascular disease, adrenal insufficiency, insulin sensitivity, and cognition." (PMID 35056103, 2021). "Adrenal insufficiency should be considered in patients with autoimmune thyroid disease or T1DM who develop non-specific illness or become seriously ill, or in diabetic patients whose insulin requirements fall inexplicably." (PMID 22839422, 2012).
Adrenal insufficiency (continued). "The insulin tolerance test (ITT) is a gold standard test assessing the hypothalamic-pituitary-adrenal axis, and the corticotropin-releasing hormone (CRH) test is useful for differentiating CAI into secondary (pituitary) and tertiary (hypothalamic) adrenal insufficiency." (PMID 35281581, 2022). "Even for patients with adrenal insufficiency, DHEA supplement for several months could not influence fasting glucose, insulin, lipids, or endothelial function." (PMID 35784547, 2022).
Sleep apnea (52 papers, 2008 to 2026). An intermittent cessation of airflow at the mouth and nose during sleep is known as sleep apnea. "An alternative explanation for these observations is that BMI/risk of sleep apnea is in the causal pathway between shorter sleep duration and increased insulin resistance." (PMID 31096629, 2019). "In summary, shorter sleep duration and poorer sleep quality were associated with higher insulin resistance, but these associations were dependent on BMI and the risk of sleep apnea." (PMID 31096629, 2019). "Nevertheless, the subjects were well characterized in terms of metabolic parameters, insulin resistance and associated sleep disordered breathing, hence providing the possibility to address several possible confounders." (PMID 25437865, 2014). "In abdominally obese men, the severity of sleep apnea seems associated with additional deleterious effect on insulin sensitivity beyond insulin resistance related to abdominal adiposity." (PMID 23951064, 2013). "In multivariable analyses, both marker of sleep apnea severity and BMI/waist circumference were associated with fasting insulin and HOMA-IR." (PMID 23951064, 2013). "The present study was designed to specifically address the respective association of abdominal adiposity and severity markers of sleep apnea with plasma glucose/insulin homeostasis indices." (PMID 23951064, 2013). "As subjects with abnormal glucose tolerance often have high insulin levels, our results are indirectly supported by a prospective study which demonstrated that high insulin levels were associated with higher incidence of sleep apnea." (PMID 21943153, 2011). "Among young adults with T1D, both diabetes distress and general emotional distress symptoms were inversely associated with cardiovascular health even when controlling for age, T1D duration, sex at birth, race, sleep apnea risk, and continuous subcutaneous insulin infusion." (PMID 39728281, 2024). "A large NC also could reflect an altered metabolic phenotype that increases sleep apnea risk via generalized inflammation and insulin resistance, which can influence local fat metabolism as well as effect respiratory control." (PMID 33907307, 2021). "Based on earlier studies, we hypothesized that both short sleep duration and bad sleep quality are associated with higher insulin resistance, but this association is likely dependent on anthropometric traits like BMI and the risk of sleep apnea." (PMID 31096629, 2019). "If insulin action were central to the pathogenesis of sleep apnea, one might expect insulin deficient, Type 1 Diabetic (T1D) individuals to have a higher incident of disordered breathing." (PMID 30127766, 2018). "Second, repeated sleep apnea in patients with OSAHS can cause hypoxia, hypercapnia, acidosis, and even lower the affinity of insulin to its receptor." (PMID 36120463, 2022). "Other factors such as illness, stress, menstruation cycle, sleep apnea, or some medications can also lead to important physiological changes, including changes in insulin sensitivity." (PMID 34770425, 2021). "In the included research studies, however, telehealth was mainly used to augment management in specific chronic diseases (e.g. sleep apnea) or support specific clinical functions (e.g. insulin therapy monitoring)." (PMID 34886863, 2021). "In fact, chronic intermittent hypoxia has been proposed as the single most crucial factor in the development of insulin resistance in those with sleep apnea." (PMID 30841553, 2019). "Chronic sleep disruption or sleep fragmentation such as that seen in sleep apnoea, also have an impact on body mass and insulin sensitivity." (PMID 30709031, 2019). "In non-obese, high-fat diet fed rats, metformin treatment increased insulin sensitivity and prevented the development of sleep apnea independently of body weight." (PMID 30127766, 2018).
Sleep apnea (continued). "In non-diabetic patients with OSA, the severity of sleep apnea is associated with adipose tissue insulin sensitivity but not whole-body insulin sensitivity." (PMID 39434962, 2023). "In addition, patients from the cAF group had significantly higher BMI values, had more often sleep apnea, and obtained more often platelet inhibitors, novel oral anticoagulants, Ca-antagonists or insulin than SR patients." (PMID 27680490, 2016). "Although the pathophysiology of this hormonal imbalance may be related to several factors, including glycemic control, concomitant sleep apnea, insulin resistance, the main role is determined by the degree of central or visceral obesity and the consequent inflammatory state." (PMID 35518937, 2022). "CB glucose sensing could be altered in diabetic patients, particularly those under insulin treatment, as well as in other medical conditions such as sleep apnea or obstructive pulmonary diseases, where chronic hypoxemia presents with plastic modifications in CB structure and function." (PMID 25360117, 2014). "In addition, there may have been some unmeasured covariates or confounders (e.g., insulin dose, sleep apnea through polysomnography, or central vs. peripheral obesity indicators such as waist circumference) contributing to the variance in cardiovascular health factors and or behaviors." (PMID 39728281, 2024). "Despite these men presented with only mild sleep apnea (AHI between 5 to 15 events/hour), they had a lower insulin sensitivity measured by ISI Matsuda index than non apneic controls." (PMID 23951064, 2013). "Moreover, even in the absence of sleep apnea, insulin resistance remains correlated with impaired mechanical function of the upper airway." (PMID 39221158, 2024). "Insulin or metformin treatment can substantially improve disordered breathing in STZ-T2D rats, suggesting that insufficient insulin action may contribute to the development of sleep apnea." (PMID 30127766, 2018). "All subjects (7M, 1F) were young (28 ± 2 years), nonobese (height 178 ± 3 cm, weight 78 ± 6 kg, BMI 25 ± 1 kg/m2), nondiabetic (fasting glucose 5.1 ± 0.2 mmol/L; fasting insulin 26 ± 6 pmol/L; HOMA‐IR 1.0 ± 0.3), without sleep apnea (apnea hypopnea index <5 events/hour)." (PMID 28087818, 2017).